HSPA2 (heat shock protein family A (Hsp70) member 2)
Diseases named in the same sentence as HSPA2 in open-access papers (continued):
Sharing a sentence is not in itself a finding about the gene and the disease.
cancer (continued). "We showed how using non-specific antibodies can generate misleading conclusions on HSPA2 expression in non-stressed cancer cells and tumors, as well as in cancer cells exposed to proteotoxic stress." (PMID 32560263, 2020). "Studies on cancer cells have not yet given conclusive results regarding the role of HSPA2 in cancer." (PMID 32987811, 2020). "In turn, the acknowledged growth-promoting role of HSPA2 in cancer cells has not been questioned so far50,55,56." (PMID 31591429, 2019). "Besides, the mRNA expression of MAGEB16, SERPINE1, HSPA2, FOS, involved in the cancer-related signaling pathways, was 1.64, 2.83, 3.62, 2.54 fold changed respectively." (PMID 26879937, 2016). "Also, a global transcriptome analysis of HeLa cells revealed strikingly distinct changes in gene expression between HSPA2- and HSPA1-depleted cancer cells." (PMID 25344376, 2015). "Although the expression of the HSPA2 gene in tumors is unquestionable, the influence of HSPA2 on the phenotype of cancer cells has not been unequivocally established." (PMID 25344376, 2015). "CNV-TFs TBP and NFYB targeted HSPA2, HSPA8 and HSPA1A respectively, three members of heat shock protein 70 which could inhibit apoptosis in cancer cells through simultaneous and independent mechanisms." (PMID 24897108, 2014). "Our results show that HBEC but not cancer cells are sensitive to HSPA2 deficit." (PMID 32987811, 2020). "One may suspect several scenarios for HSPA2 significance in cancer and corresponding non-tumorigenic cells." (PMID 32987811, 2020). "First, HSPA2 may gain new crucial importance in cancer cells while being non-essential in corresponding non-transformed cells." (PMID 32987811, 2020). "A lack of consensus on the HSPA2 significance in cancer cells may suggest that both the regulation of the HSPA2 expression and contribution of the encoded chaperone to the biology of normal versus tumor cells are complex." (PMID 32987811, 2020). "Secondly, HSPA2 may have essential but different contributions to the phenotype of cancer and corresponding non-transformed cells." (PMID 32987811, 2020). "The available evidence indicates that HSPA2 may have different prognostic value than HSPA1, a major stress-inducible and the most thoroughly investigated chaperone from the HSPA (HSP70) family, also frequently over-represented in cancer." (PMID 31591429, 2019). "Interestingly HSPA2 is required for survival of cancer cells, while non-tumorigenic cells (mammary MCF-10A, HBL-100, and prostate PNT1A) displayed no changes in survival after depletion of HSPA2." (PMID 21496299, 2011). "Interestingly, EVs containing HSPA2 are also released by non-stressed cancer and normal cells." (PMID 36959387, 2023). "Because high HSPA2 expression was associated with negative prognosis in esophageal SCC, non-small cell lung cancer (NSCLC), and liver hepatocellular cancer (HCC) patients, it seems that this protein could be a clinically relevant cancer biomarker." (PMID 25344376, 2015). "HSPA2, one of stress-non-inducible and least characterized members of the HSPA family (HSP70), is ubiquitous in various types of cancer cells." (PMID 39149564, 2024). "Analysis of HSPA2 and CCT1 expression did not reveal statistical difference between cancer and normal tissue (p > 0,05)." (PMID 31101846, 2019). "HSPA2 and HSPA4 did not seem to be affected in different types of cancer." (PMID 34692733, 2021).
tumor (24 papers, 2011 to 2025). "In NSCLC patients, nuclear HSPA2 expression was associated with histology, tumor-node-metastasis staging, and prognosis." (PMID 37570716, 2023). "HSPA2 overexpression is associated with tumor angiogenesis, invasive progression, and poor prognosis." (PMID 34059060, 2021). "Accordingly, immunohistochemistry-based studies linked a high level of HSPA2 in tumor with unfavorable clinicopathological characteristics and shorter overall as well as disease-free survival." (PMID 32987811, 2020). "The mechanism of a mutated HSPA2 chaperone has a dominant effect in tumor cells by triggering the G2/M phase transition during the mitotic cell cycle, which could explain the HSPA2 abnormal expression in somatic tumors." (PMID 23777267, 2013). "Concordant increased tumour gene expression and plasma protein expression was only found for HSPA2 and KIAA0319 in the CAC group." (PMID 37045997, 2023). "A significant relationship was observed between the excessive expression of HSPA-2 and important prognostic parameters such as macroscopic tumor size, lymphovascular invasion, pT, pN, pM, TNM stage, recurrence, and survival rates." (PMID 35703525, 2022). "On the other hand, they also observed positivity with HSPA-2 in infiltrative areas in half of their cases, while there was no positivity in the normal epithelium in areas adjacent to the tumor in SCC in the head and neck region." (PMID 35703525, 2022). "Evaluating the results of our study and the available data in the literature together, we consider that HSPA-2 can be involved in carcinogenesis, tumor development, progression, and metastasis." (PMID 35703525, 2022). "The overexpression of HSPA-2 was statistically significantly correlated with prognostic parameters, namely macroscopic tumor size, lymphovascular invasion, pT, pN, pM, TNM stage, and recurrence (P < .05)." (PMID 35703525, 2022). "In our study, the emergence of the tumor suppressive functions of HSPA2 was supported by the decreasing HSPA2 expression in larger and more advanced tumors." (PMID 31101846, 2019). "Using univariate Cox regression analysis followed by multivariate Cox regression analysis, we built a risk score formula comprising prognostic HSPs (HSPA2, DNAJC20, HSP90AA1, CCT1, CCT2) and tumor stage to identify high-risk and low-risk cases." (PMID 31101846, 2019). "The result indicated JAG1 and HSPA2 were heterogeneously expressed in tumor parts and partially colocalized." (PMID 26930648, 2016). "Clinicopathological analysis showed that HSPA2 expression was significantly correlated with tumor size (P = 0.024), histological differentiation (P = 0.012), TNM stage (P = 0.006), lymph node metastasis (P = 0.043) and serum CA19-9 level (P = 0.046)." (PMID 25890028, 2015). "Hypermethylation was associated with advanced tumor stage for ABCC6 (P = 0.050), BRCA1 (P = 0.032), CDH1 (P = 0.004), GDF15 (P = 0.005), HSPA2 (P = 0.000), RASSF1A (P = 0.003), TSHB1 (P = 0.018), and TMEFF2 (P = 0.002)." (PMID 25613404, 2015). "It therefore seems evident that in these cases, the expression of the HSPA2 gene is initiated during tumor development." (PMID 25344376, 2015). "Hypermethylation was associated with advanced tumor grade for BRCA1 (P = 0.003), CDH1 (P = 0.002), HSPA2 (P = 0.009), RASSF1A (P = 0.017), and THBS1 (P = 0.000), while methylated GDF15 (P = 0.002) promoter was associated with low tumor grade." (PMID 25613404, 2015). "One of the most intriguing issues concerning the potential influence of HSPA2 on the phenotype of tumor cells emerges from the comparison of the HSPA2 expression pattern in primary tumors and in the corresponding normal tissues." (PMID 25344376, 2015). "Since HSPA2 shuttles continuously between the cytoplasm and nucleus during heat-shock, this cell migration is critical for tumor formation and metastasis." (PMID 23777267, 2013). "We also found that HSPA2 mRNA had different expression levels in the ESCC tissues at different tumor stages." (PMID 23777267, 2013).
tumor (continued). "Silencing the expression of the HSPA2 gene by RNA interference suggests that HSPA2 increases the growth rate and tumorigenic potential not only in the cell culture but also in tumor xenograft in mice." (PMID 23777267, 2013). "HSPA2 is not only essential for spermatogenesis, but is required for tumor cell growth and survival." (PMID 21496299, 2011). "Additionally, miR-634 acts as a tumor suppressor by targeting HSPA2, inhibiting epithelial-to-mesenchymal transition and extracellular matrix degradation." (PMID 41148842, 2025). "RNF144A interacted with HSPA2 can promote tumor growth and progression." (PMID 34412642, 2021). "The data presented in this paper clearly show that using non-validated and/or non-specific antibodies may undermine the reliability of conclusions on HSPA2 as a prognostic tumor marker." (PMID 32560263, 2020). "Recently, research has shown that human tumor cells can express HSPA2 at high levels." (PMID 25890028, 2015). "The intriguing issue concerns the role of the HSPA2 gene in human tumor cells." (PMID 25344376, 2015). "Our recent immunohistochemical study with the use of tissue microarrays demonstrated that the HSPA2 protein is widely expressed in human malignancies, although the percentage of HSPA2-positive samples may vary between different tumor histotypes." (PMID 25344376, 2015). "In addition, HSPA2 mRNA was expressed at significantly higher levels in patients with larger tumor sizes (P = 0.024)." (PMID 25890028, 2015). "Lastly, a new regulatory mechanism of HSPA2 expression in tumor cells has been disclosed, which suggests that the upregulation of HSPA2 enhanced the resistance of tumor cells to hypoxia-induced apoptosis, which provides a new insight into how tumor cells overcome hypoxic stress and survive." (PMID 23777267, 2013). "The abnormal excessive proliferation of tumor cells also frequently occurs in late stages and overexpression of HSPA2 can promote development of the CDC2 kinase activity, required to trigger G2/M phase transition and regulate cell proliferation through controlling cell cycling." (PMID 23777267, 2013). "Downregulation of MHC genes that are involved in antigen presentation, including HLA-B/-C/-F/-G, and genes responsible for antigen processing, CTSB and HSPA2, may facilitating tumor cell evasion of immunosurveillance and, hence, increase tumor cell survival." (PMID 23024765, 2012). "Additionally, the validation of other commercial antibodies used for HSPA2 detection in the testes (e.g., antibody SAB1405970 from Sigma-Aldrich; antibody sc-100760 from Santa Cruz Biotechnology) should precede their usage for HSPA2 analysis in somatic tissues or tumor samples." (PMID 32560263, 2020). "Interestingly, among these HSPs, overexpression of HSPA2 and DNAJC20 was associated with better prognosis (tumor suppressor-like activity), whereas high expression of other heat shock genes (HSP90AA1, CCT1, CCT2 and CCT6A) correlated with poor survival (oncogene-like activity)." (PMID 31101846, 2019). "Hsp70s, including HSPA8, HSPA2, and HSPA1B, could be either tumor-promoting or tumor-suppressing depending on cell identity and context." (PMID 36120453, 2022). "So far, there are no data concerning HSPA2 expression in tumors and tumor cells of rats and mice." (PMID 25344376, 2015). "Similarly, Zhang et al15 reported that while they did not observe staining with HSPA-2 in normal esophagus epithelial tissue, they detected poor staining in areas adjacent to the tumor and in the squamous epithelium basal layer and stronger staining in infiltrative areas." (PMID 35703525, 2022).
infection (5 papers, 2014 to 2024). The state of being infected such as from the introduction of a foreign agent such as serum, vaccine, antigenic substance or organism. "We speculate that cells decrease the expression of HSPA2 by themselves to protect them from infection and damage from HEV." (PMID 25175408, 2014). "This fluctuation contrasts with certain HSP70 isoforms, where several are upregulated (e.g., HSPA1L, HSPA2, HSPA5, HSPA9, HSPA12, and HSPA13), while others from the HSP70 family are downregulated post-peak infection phase (Chand, Iyer & Mitra, 2021)." (PMID 39308823, 2024). "Five unique heat shock proteins (HSP75, HSP90A, HSPA2, HSPA5 and HSPA8) were identified during rNA-wt infection." (PMID 28079188, 2017). "Infection of rSD20 in CEF cells was characteristic of regulated LMNA, HSPA2 and FKBP4." (PMID 28079188, 2017).
adenocarcinoma (2 papers, 2016 to 2020). A common cancer characterized by the presence of malignant glandular cells. "Recently, HSPA2 was reported that it was expressed in SCC rather than in adenocarcinoma and correlated with poor overall survival, supporting our finding in SCC." (PMID 26930648, 2016).
cardiac disease (1 paper, 2019). "In our mass-spectrometry-based proteomics study, HSPA2 was highly upregulated in cardiac disease." (PMID 31323898, 2019).
HSPA2 also shares sentences with these, for which no sentence is quoted: colon cancer (4 papers); Azoospermia (3); Alzheimer disease (2); autoimmune disease (1); bladder tumors (1); breast tumors (1); cerebral artery (1); chronic myeloid leukemia (1); colorectal cancer (1); dementia (1); endometrial cancer (1); esophageal cancer (1); infectious disease (1); laryngeal squamous cell carcinoma (1); legionellosis (1); leiomyoma (1); leiomyosarcoma (1); meningioma (1); metabolic disorders (1); Neurofibrillary tangles (1); renal carcinoma (1); schizophrenia (1); Skin ulcer (1); squamous cell carcinoma (1); stomach adenocarcinoma (1); testis cancer (1); type 1 diabetes (1); type 2 diabetes (1).